KLHDC1 (kelch domain containing 1)
Description:
Substrate-recognition component of a Cul5-RING (CRL5) E3 ubiquitin-protein ligase complex of the DesCEND (destruction via C-end degrons) pathway, which recognizes a C-degron located at the extreme C terminus of target proteins, leading to their ubiquitination and degradation. The C-degron recognized by the DesCEND pathway is usually a motif of less than ten residues and can be present in full-length proteins, truncated proteins or proteolytically cleaved forms. The CRL5(KLHDC1) complex mediates ubiquitination and degradation of truncated SELENOS selenoprotein produced by failed UGA/Sec decoding, which ends with a glycine.
Synonyms: MST025
Tractability: No criterion of Open Targets' tractability assessment is met for any kind of drug.
Gene: Protein-coding gene on chromosome 14 (49,693,105 to 49,753,636, forward strand). Ensembl gene ENSG00000197776.
Subcellular location: Cytoplasm, cytosol
Subcellular location (Human Protein Atlas): Cytosol
Gene Ontology:
Molecular function: ubiquitin-like ligase-substrate adaptor activity
Biological process: ubiquitin-dependent protein catabolic process via the C-end degron rule pathway; protein ubiquitination
Cellular component: Cul5-RING ubiquitin ligase complex; cytoplasm; cytosol; cullin-RING ubiquitin ligase complex
Genetic constraint (gnomAD): Loss-of-function variants: 6 observed, 2.89 expected, observed/expected ratio (o/e) 2.07. That is too few expected variants to judge how well the gene tolerates losing a copy. Missense variants: 75 observed, 53.83 expected, observed/expected ratio (o/e) 1.39, 90% interval 1.15 to 1.69. Synonymous variants: 34 observed, 21.25 expected, observed/expected ratio (o/e) 1.6, 90% interval 1.2 to 1.93.
Homologues: Orthologues: chimpanzee KLHDC1 (99% identical), macaque KLHDC1 (99% identical), pig KLHDC1 (94% identical), dog KLHDC1 (94% identical), rabbit KLHDC1 (92% identical), guinea pig KLHDC1 (92% identical), rat Klhdc1 (89% identical), mouse Klhdc1 (89% identical), tropical clawed frog klhdc1 (63% identical), Drosophila melanogaster Hcf (22% identical), Caenorhabditis elegans hcf-1 (21% identical). Paralogues in human: KLHDC2 (41% identical), HCFC1 (23% identical), HCFC2 (23% identical), LZTR1 (22% identical), KLHDC10 (21% identical), KLHDC3 (20% identical), KLHDC4 (20% identical), RABEPK (18% identical), FBXO42 (17% identical), KLHDC9 (14% identical).
Diseases named in the same sentence as KLHDC1 in open-access papers:
KLHDC1 is named in the same sentence as 3 diseases in open-access papers, as found by Europe PMC text mining. Sharing a sentence is not in itself a finding about the gene and the disease. The quoted sentences say what the papers report.
cancer (1 paper, 2023). A tumor composed of atypical neoplastic, often pleomorphic cells that invade other tissues. "KLHDC1 knockdown reduces endoplasmic reticulum stress-induced cell death, which is essential for maintaining reactive oxygen species levels and preventing cancer development." (PMID 36855119, 2023).
tumor (1 paper, 2022). "The most significant target genes were putative tumor oncogenes/promoters (TK1, KIF2C, UBE2C, AURKB) and potential tumor suppressors (CALCOCO1, CIRBP, KLHDC1, CBX7)." (PMID 36358602, 2022).
KLHDC1 also shares sentences with these, for which no sentence is quoted: glioma (1 paper).